FTL (ferritin light chain)
Diseases named in the same sentence as FTL in open-access papers (continued):
Sharing a sentence is not in itself a finding about the gene and the disease.
infection (18 papers, 2010 to 2025). The state of being infected such as from the introduction of a foreign agent such as serum, vaccine, antigenic substance or organism. "Cell migration and invasion assays illustrated that FTL-silenced infection significantly impaired ESCC cells motility." (PMID 41281761, 2025). "After the infection, in the Fe-Gly addition group, the expression of hepatic FTL gene was significantly decreased (p < 0.05), the expression of HAMP gene tended to decrease (p = 0.050), and the expression of FTH gene had a tendency to decrease (p = 0.051)." (PMID 39944187, 2025). "Under infection conditions, the addition of Fe-Gly group showed a tendency to reduce the expression of jejunal FTL gene compared with the control group (p = 0.076)." (PMID 39944187, 2025). "No significant changes in the expression levels of the ferritin subunits (FtH and FtL) and transferrin receptor 1 (Tfr1) were observed in response to the infection across different genotypes at both the protein and mRNA level, respectively." (PMID 38301068, 2024). "Surprisingly, we found that the increase in serum ferritin observed in Fth1+/+ mice upon infection was due to increases in both FTL and FTH1 chains." (PMID 35008695, 2021). "Serum ferritin (mainly FtL) is used to measure body iron stores in healthy individuals but its increased level in response to infection and inflammation limits its utility." (PMID 30804939, 2019). "In contrast, our findings predominantly emphasize the significance of circulating FtL in modulating inflammatory cells toward a restrained response to infection." (PMID 30804939, 2019). "Our analysis revealed a significant increase in both mRNA and protein expression of FTH1, FTL, and TFR1 following infection with N. seriolae." (PMID 39717544, 2024). "Ferritin heavy chain 1 (FTH1), ferritin light chain (FTL), mitochondrial ferritin (FTMT), and ATP6V1F were the downregulated genes identified in A. baumannii without resistant gene infection-associated pulmonary host response." (PMID 39857726, 2025).
neurodegenerative disease (14 papers, 2010 to 2024). A disorder of the central nervous system characterized by gradual and progressive loss of neural tissue and neurologic function. "Iron accumulation in the nervous system in neurodegenerative diseases is also caused by defects in the human FTL gene." (PMID 39619616, 2024). "FTL is a component of ferritin, and defects in this subunit are associated with other neurodegenerative diseases where mutations result in accumulation of iron in the brain." (PMID 26550040, 2015). "The brain accumulates iron over time, especially in neurodegenerative disease conditions, and reactive astrocytes may upregulate FTL to sequester excess iron and inhibit neuron death." (PMID 37533101, 2023).
autosomal dominant disease (3 papers, 2015 to 2023). Autosomal dominant form of disease. "Hereditary hyperferritinemia-cataract syndrome (HHCS) is a rare, frequently misdiagnosed, autosomal dominant disease caused by mutations in the FTL gene." (PMID 37569253, 2023).
bacterial infection (3 papers, 2015 to 2025). "Ferritin, light polypeptide (FTL) is involved in iron homeostasis, and the differential usage of PA sites from FTL in uninfected and early interacting host cells could contribute to the early response following bacterial infection." (PMID 26697380, 2015). "Of note, seroconversion is not strongly correlated with changes in acute phase proteins that are commonly elevated upon viral and bacterial infections, such as C-reactive protein (CRP) and ferritin (FTL)." (PMID 33724185, 2021).
brain disorder (1 paper, 2022). A disease affecting the brain or part of the brain. "All three ferritin protein levels decreased in brain disorders particularly in DS and very low levels of FTL were visible in the periphery of senile plaques." (PMID 35162984, 2022).
kidney (1 paper, 2024). "Myeloid FtL deficiency does not impact LPS-induced acute kidney injury." (PMID 38779751, 2024).
FTL also shares sentences with these, for which no sentence is quoted: aceruloplasminemia (3 papers); cardiac hypertrophy (2); cognitive decline (2); depression (2); Parkinson disease (2); abscess (1); autism (1); autosomal dominant cataract (1); bladder cancer (1); brain iron accumulation (1); cervical cancer (1); congenital cataracts (1); dyslipoproteinemic corneal dystrophy (1); endometriosis (1); esophageal squamous cell carcinoma (1); glaucoma (1); hemochromatosis (1); Hepatic steatosis (1); Hepatitis (1); juvenile rheumatoid arthritis (1); kidney injury (1); metastatic cancer (1); mevalonic aciduria (1); movement disorder (1); multiple sclerosis (1); myocardial infarction (1); myocardial ischemia (1); neurodegeneration with brain iron accumulation (1); oligodendroglioma (1); Onset (1).
A further 12 diseases each share a sentence with FTL in 1 paper.